IL15 (interleukin 15)
Diseases named in the same sentence as IL15 in open-access papers (continued):
Sharing a sentence is not in itself a finding about the gene and the disease.
tumor (continued). "In this study, we found that transfer of syngeneic NK cells conditioned using IL-15 and IL-12 after resecting the primary tumor resulted in long-term survival of mice with low burden lung metastases." (PMID 39835538, 2025). "The combination of CD25-targeted NIR-PIT and intratumoral IL-15 with anti-PD-1 mAb suppressed tumor growth, prolonged survival and increased the CD8+/Treg ratio." (PMID 41410776, 2025). "Our findings demonstrate superior synergy between NK cell-redirected BsAbs and IL-15 fusion, achieving >90% tumor lysis in vitro and significant regression in xenograft models." (PMID 40873574, 2025). "In preclinical models, IL-15 has improved tumor regression and survival outcomes by promoting the infiltration and activation of cytotoxic lymphocytes within tumors." (PMID 40227601, 2025). "To characterize the distribution of IL-15 complexes and anti-PD-1 mAb in situ and track the interactions with immune cells within the tumor, we fluorescently labeled IL-15Rα-Fc with Cy5 and anti-PD-1 mAb with Cy3." (PMID 41373645, 2025). "One notable example involved the engineering of γδ T cells to secrete synthetic tumor-targeting opsonins and a mitogenic IL-15Rα-IL-15 fusion protein (stIL15) in osteosarcoma." (PMID 40227601, 2025). "To address this gap, we developed a modular immunotherapy platform combining B7-H6-specific BsAbs with a tumor-anchored IL-15/IL-15Rα sushi fusion protein." (PMID 40873574, 2025). "Increasing NK cell infiltration through adoptive NK cell transfer or cytokine stimulation (e.g., IL-15 administration) can enhance anti-tumor immunity in osteosarcoma." (PMID 40170852, 2025). "To date, tumor-directed delivery of IL-15/4-1BBL (scFv anti-FAP), IL-2/TNF (scFv anti-EDA) and IL-2/IL-12 (scFv-Fc anti-CD30, LAIR2), has shown significant therapeutic effects in preclinical tumor mouse models." (PMID 40370435, 2025). "Biomimetic IL-15 nanovaccines demonstrated superior tumor suppression across multiple models, with 3 out of 6 mice showing complete absence of visible tumors in post-surgical recurrence models." (PMID 40791791, 2025). "mRNAs coding for cell-associated cytokines (IL-15, IL-12) and costimulatory molecules (OX40L) activate T cells and NK cells, showing anti-tumour efficacy in solid tumours and myeloid malignancies." (PMID 41586257, 2025). "As expected, incubation with MC38 tumor homogenate, which is rich in intratumoral proteases, resulted in the significant release of HA-tagged IL-15, whereas less cleavage was observed with liver, lung, or kidney homogenates." (PMID 40532661, 2025). "CAR-T cells engineered to co-express IL-15 have demonstrated enhanced expansion, persistence, and antitumor activity across different tumor models." (PMID 40771804, 2025). "Peripheral NK cells can differentiate into ieILC1-like NK cells via co-culture with HNSCC tumor cells and IL-15, and the ex vivo differentiated ieILC1-like NK cells are robust producers of IFNγ and CD107a upon stimulation." (PMID 40114916, 2025). "Recent research has shown that the expansion of γδT cells with cytokines such as IL-15 and IL-12 leads to the preferential growth of cytotoxic γδT cells, which exhibit superior anti-tumor effects." (PMID 40226616, 2025). "CAR-T cells cultured ex vivo and supplemented with IL-2 exhibited the least anti-tumor effect compared to the combination of IL-15 and IL-21." (PMID 40291594, 2025). "Integrating these PD-L1 haNK cells with anti-PD1 and N-803, an IL-15 super agonist, demonstrated superior tumor growth control in preclinical models." (PMID 41511303, 2025). "Interleukin‐15 (IL‐15) promoted ILC1 granzyme A expression and cytotoxicity, and IL‐15 expression in chRCC tumour tissue positively tracked with the ILC1 response." (PMID 40801800, 2025). "When IL-15/IL-15Rα is combined with a PD-L1-specific antibody (K2-Fc), it further enhances tumor cell killing by boosting NK-cell activation independently of T cells." (PMID 40636453, 2025).
tumor (continued). "The B7-H6M18/IL-15/IL-15Rα sushi fusion protein enables tumor-localized cytokine activation while preserving effector cell specificity." (PMID 40873574, 2025). "highlight that ILC1s exhibit cytotoxicity against cancer cells and can be pre-activated with IL-12 or IL-15 to enhance their anti-tumor efficacy." (PMID 40963622, 2025). "By investigating tumor response, quality of life, and biomarker changes, this clinical research aims to provide insights into the potential of IL-15-based immunotherapy to enhance existing treatment protocols in veterinary oncology." (PMID 40520425, 2025). "The use of irradiated K562 cells modified to express membrane-bound interleukin-15 (mbIL-15) and 4-1BB ligand has markedly enhanced NK cell proliferation, survival, and cytotoxicity against tumor targets." (PMID 40564987, 2025). "Application of IL-15 caused peripheral NK cell activation, which in turn induced IFN-γ expression, leading to systemic toxicity and tumor progression." (PMID 40469178, 2025). "This is consistent with the role of T lymphocytes-particularly CD8+ T cells-in suppressing tumor growth via cytokine production, such as IL-2 and IL-15, and direct cytotoxic activity." (PMID 41367471, 2025). "The combination of mRNAs encoding IL-15, IL-12, and OX40L enhances anti-tumour treatment by efficiently activating T cells and NK cells." (PMID 41586257, 2025). "Although no head-to- studies have been conducted comparing the effects of IL-7 vs IL-15 to increase tumor trafficking, IL-15 can also strongly enhance tumor trafficking via its effects to increase lymphocyte adhesion molecules and chemokines." (PMID 41550947, 2025). "Although research on the role of IL-15 in PC remains limited, recent studies have highlighted its potential as a mediator in exercise-induced tumor immunity." (PMID 40948749, 2025). "CD70 chimeric antigen receptor natural killer cells (CD70-CAR-NK), engineered with IL-15, hnCD16, and CD70 knockout, target tumor cells and cancer-associated fibroblasts with minimal off-tumor effects, exhibiting potent cytotoxicity and prolonged persistence." (PMID 40896423, 2025). "CD56bright NK cells, often regarded as “amateur” NK cells in comparison to CD56dim NK cells, have been found to exert a more robust anti‐tumor effect in the presence of IL‐15." (PMID 39811936, 2025). "IFN-I signaling in cDCs, including that induced by STING agonists, upregulates the expression of IL-15/IL-15Rα by cDCs, which is thought to augment anti-tumor immunity via the activation of cDCs, CD8+ T cells, and natural killer (NK) cells." (PMID 40227734, 2025). "The ability of IL-15 complexes to migrate to the tumor-draining lymph node is critical for activating NK and CD8+ T cells." (PMID 41373645, 2025). "Paradoxically, there was an enrichment of IL-15 signalling induced LRPs, which promotes anti-tumour immunity through NK-cell mediated tumour killing, although IL-15 has also been reported to have pro-tumoral activity in solid cancers." (PMID 40280979, 2025). "IL15 exhibited negligible benefits in immunocompetent mice and paradoxically accelerated tumor growth by 66% in immunocompromised counterparts." (PMID 39625860, 2025). "Glypican-3-CAR T cells have previously been developed as second-generation constructs, subsequently corroborated by the co-secretion of soluble cytokines like IL-15 and/or IL-21 for the improvement of anti-tumor function." (PMID 41465318, 2025). "This was further validated in RMS mouse models, where NK cells pretreated with IL-12, IL-15, and/or IL-21 resulted in significant tumor growth inhibition." (PMID 41007114, 2025). "Using our combination treatment of IL-15 complexes and anti-PD-1 blockade, which induces tumor immunity, we show that the integrin Itga6 is downregulated." (PMID 41373645, 2025). "IL-15 is a cytokine that induces the activation of NK and T cells in the intestinal mucosa and exhibits tumor-suppressive effects." (PMID 40431182, 2025).
tumor (continued). "Tumor-restricted IL-15 delivery reduced systemic toxicity while enhancing effector cell persistence, a critical advantage for treating chemoresistant malignancies like small-cell lung cancer (SCLC)." (PMID 40873574, 2025). "Other alternatives include the pre-activation of NK cells with cytokine preconditioning (e.g., IL-12, IL-15, and IL-18), which can generate memory-like NK cells with enhanced persistence, metabolic fitness, and prolonged anti-tumour responses." (PMID 40624498, 2025). "Here, we developed a protease-sensitive IL-15-engineered bacterial system for tumor-targeted therapy." (PMID 40532661, 2025). "Ex vivo cytokine induction with IL-12, IL-15, and IL-18 creates a “memory-like” phenotype, enhancing proliferation, persistence, and tumor recognition." (PMID 41375063, 2025). "CD8+ effector and tissue-resident T cells expressed numerous IL-related receptor genes; however, they lacked stimulation from IL-related cytokines such as IL-2, IL-4, IL-7, and IL-15 when comparing response states between tumor and healthy groups." (PMID 40698080, 2025). "MC38 tumor-bearing mice received either EcN-IL-15 (4 × 107 colony-forming unit [CFU], two injections) or mouse IL-15 at doses of 5 μg (low dose, L, four injections) or 10 μg (high dose, H, four injections)." (PMID 40532661, 2025). "Preclinical data show that TROP2 is frequently overexpressed in OC, and CAR-NK cells armed with cytokine support (IL-15) exhibit potent tumor cell killing." (PMID 40643516, 2025). "IL-15 can enhance NK cell functionality; thus, it has been of interest to develop strategies to enhance NK cell mediated anti-tumor immunity using this cytokine." (PMID 38515757, 2024). "This shift will increase the immunosuppressive cytokines (IL-2, IL-4, IL-7, IL-13, and IL-15) production by neoplastic elements which lead to tumor growth and spread." (PMID 38850434, 2024). "In an orthotopic GBM mouse model, the combination of oncolytic virus expressing IL15/IL15Rα and EGFR-CAR-NK cells causes a strong anti-tumor response." (PMID 38664743, 2024). "IL-7, which has demonstrated strong effectiveness in fighting tumours when used alone, can also be utilised in combination with other cytokines such as IL-12, IL-15, and GM-CSF." (PMID 38675377, 2024). "In a transplanted tumour murine model, treatment with IL‐15 significantly suppressed tumour growth in Tigit−/− mice compared to WT littermates." (PMID 38279870, 2024). "Taken together, cultivation based on IL-15 or IL-18 stimulation should be considered when appropriate persistency and anti-tumor functions of Vγ9Vδ2 T cells are required." (PMID 38221530, 2024). "CAR T cells engineered to secrete IL-15 have been shown to exhibit increased tumor cytotoxicity compared to using CAR alone T cells in vitro and in vivo studies." (PMID 39835140, 2024). "CAR70/IL-15 NK cells from Opt-Cs resulted in significantly better tumor control, in vivo proliferation and superior survival compared to their Sub-C counterparts." (PMID 38238616, 2024). "CAR-T cells effectively eliminate tumor cells through the release of perforin, granzymes, and cytokines, such as IL-1, IL-6, IL-15, interferon-gamma (IFN-γ), and GM-CSF." (PMID 38550613, 2024). "The results of the study showed that rIL7/IL15 inhibited tumour growth in a dose-dependent manner by approximately 60% at the 2.5 μg level and >80% at the 20 μg level, which are both superior to cytokine monotherapy in terms of anti-tumour effect." (PMID 38675377, 2024). "The migration of IL-15-overexpressing tumor cells was significantly compromised by the addition of LY294002 or rapamycin." (PMID 38637902, 2024). "Patients in situations like this would likely benefit from targeting tumor dormancy with further immunotherapy strategies such as cytokines (IL-15) that reinvigorate antitumor effector cells such as NK cells and CD8+ T cells." (PMID 39496729, 2024).
tumor (continued). "In vitro studies have demonstrated that IL-15 can restore depleted NK cell mitochondria integrity in the tumor microenvironment, enhance cytotoxicity, and promote IFN-γ generation." (PMID 39221244, 2024). "Both in vitro and xenograft models displayed that FCRL5 CAR-T cells incorporating IL-15 exhibited potent antitumor efficacy, effectively inhibiting the proliferation of MM cells and leading to remarkable tumor suppression." (PMID 38212320, 2024). "As intracellular and extracellular IL-15 clearly differentially regulate cell migration, we investigated how the migration of tumor cells is regulated by both cell-intrinsic IL15 and extracellular IL-15." (PMID 38637902, 2024). "To understand these seemingly inconsistent conclusions, we utilized a mouse model to examine the role of cancer cell-intrinsic IL-15 in tumor growth in vivo." (PMID 38637902, 2024). "Second-generation TriKEs contain cam16, a humanized single-domain anti-CD16 nanobody, an IL-15 moiety, and a tumor targeting single-domain antibody (sdAb) or single-chain variable fragment (scFv)." (PMID 38545115, 2024). "IL-15 supports the development and function of NK cells and memory T-cells, contributing to sustained anti-tumor immunity." (PMID 38558795, 2024). "The selected doses were informed by findings from the biodistribution experiments and aimed to retain IL-12 at the tumor but deliver IL-15 to both the tumor and the TDLNs." (PMID 39112631, 2024). "Silencing and overexpression techniques were used to modify endogenous IL-15 expression in tumor cells." (PMID 38637902, 2024). "IL1RA, IFNα, and IL15 regulate innate and adaptive immune responses and exhibit antitumor activity, including direct tumor cell killing and stimulating immune cells, e.g., dendritic cells and CD8+ T cells." (PMID 38856749, 2024). "In contrast to what we observed for GT-00AxIL15, in vivo anti-tumor effects of other IL-15 (super)agonists on primary tumor growth are rather weak when applied as monotherapy." (PMID 38338686, 2024). "Deletion of CISH (a negative regulator of IL-15 signaling pathways) in iPSC-derived iNK cells can promote in vivo persistence and enhance the anti-tumor activity of the NK cells." (PMID 39664387, 2024). "ILC1s have been shown to infiltrate tumours upon cellular transformation in spontaneous murine cancer models, and exert cytotoxicity against tumour cells in response to interleukin-15 (IL-15)." (PMID 38745765, 2024). "The constitutive expression of IL-15 increases the anti-tumor activity of specific CAR-T cells targeting CD19, CLL-1, IL-13Rα2, GD2, and GPC-3." (PMID 38664743, 2024). "In vitro, IL-15 induced the proliferation of CD28–PD-1 + CD8 + tumor-infiltrating lymphocytes (TIL) cells more effectively than anti-PD-1 antibodies." (PMID 39507777, 2024). "We observed significantly higher frequencies of circulating CAR19 + NK cells and lower tumor burden in the bone marrow of animals treated with CAR19/IL-15 NK cells from Opt-Cs compared to those from Sub-Cs." (PMID 38238616, 2024). "The results of clinical trials showed that administration of the IL15 super-agonist complex ALT-803 enhanced the anti-tumor effect of responsive T cells." (PMID 39650651, 2024). "Numerous clinical trials have reported that drugs developed on the basis of IL-15, such as recombinant human single-chain IL-15 and IL-15 super agonists, have better efficacy in tumor therapy." (PMID 39539553, 2024). "This systemic activation contributes to the anti-tumoral effects, but GT-00AxIL15 adds the benefit of targeting and retention in the tumor, thereby further enhancing local IL-15 concentrations in relation to the tolerable overall exposure." (PMID 38338686, 2024). "Here, Cairo and colleagues developed a CAR NK cell targeting MCAM and demonstrated its anti-tumor efficacy, alone and in combination with an IL-15 agonist (NKTR-255), to circumvent NB TME resistance." (PMID 39554906, 2024).
tumor (continued). "In mammals, IL-15 regulates apoptosis and inflammatory responses and plays an important role in tumor immune surveillance." (PMID 39628491, 2024). "NK cells were supported with i.p. recombinant human IL-15 (rhIL-15) three times per week, tumor burden was measured via bioluminescence imaging (BLI)." (PMID 38805302, 2024). "The transgenic expression of IL15 can promote the expansion, survival, and function of T cells ex vivo and in vivo and enhance their anti-tumor activity." (PMID 39650651, 2024). "Physical activity also triggers the secretion of substances, such as myokines IL‐15 or IL‐6 within muscle tissue, initiating the redistribution of immune cells and eventual infiltration of the tumor site to eradicate tumor cells." (PMID 38234174, 2024). "CAR19/IL-15 NK cells were generated using our standard protocols and their antitumor efficacy tested in a tumor rechallenge assay in vitro." (PMID 38238616, 2024). "Although the pivotal role of IL-15 in enhancing NK cell- and T-cell-mediated antitumor immune responses is well recognized, few studies have investigated the direct effect of IL-15 on tumor cells." (PMID 38637902, 2024). "Notable, IL-15, IL-18, IL-1β, and TNFα in the host serum, potentially derived from the tumor microenvironment through various pathways, promoted sustained angiogenesis involving endothelial cells." (PMID 39451257, 2024). "This suggests that IL‐15 stimulation in combination with TIGIT blockade can greatly augment the activity of preexisting tumour antigen‐specific CD8+ T cells and promote tumour‐specific immune responses." (PMID 38279870, 2024). "On the contrary, a certain level of IL-15 was detected after 12 C CAR-NK cells killing multiple tumor cell lines." (PMID 39462383, 2024). "Functional evaluation of CD70-directed CAR NK cells indicated that IL-15 stimulation is essential to obtain effective elimination of CD70+ tumor cells and CAFs, and to improve tumor burden and survival of mice bearing CD70+ tumors." (PMID 38331849, 2024). "To ask whether IL-15:IL-15Ra complexes caused the emergence of CD49a+ CD11b+ cells after entry into the tumor, or if these cells were formed in the periphery and trafficked into the tumor, we photoconverted tumors and compared the % KR expression within different intratumoral NK cell subsets." (PMID 38267402, 2024). "The results highlighted that compared with IL-15–pretreated NK cells, IL-12/15/18–preactivated NK cells display greater frequency, persistence, proliferation, and functional killing activity at the tumor site." (PMID 39020411, 2024). "Upon no activation differences were observed, we expanded CAR T cells with IL15 and IL21 because recent studies show that combined expression of IL-15 and IL-21 result in a less differentiated profile and longer survival in repeated exposures to tumor cells." (PMID 39478867, 2024). "In this study, stimulation of NK cells with PM21-particles derived from K562-41BBL-mbIL21 cells was combined with memory-like induction using cytokines IL-12, IL-15, and IL-18 to produce NK cells with enhanced anti-tumor function." (PMID 38711506, 2024). "TRACK-NK cells are PD-L1+ NK cells derived from cord blood and engineered to express soluble IL-15 (sIL-15), with an ability to express high levels of tumor-reactive receptors that recognize “tumor stress”, including DNAM-1, NKp30, and NKG2D." (PMID 39518043, 2024). "Recent studies have suggested that interleukins, like IL-15 elicit changes in natural killer cells that subsequently provide anti-tumor functionality and can remain active for weeks after first cytokine stimulation." (PMID 38812776, 2024). "We developed GT-00AxIL15 as first-in-class IL-15-based immunocytokine targeting a tumor-associated, glycosylated epitope of MUC1 (TA-MUC1) to optimize tumor accumulation, efficacy, safety and half-life of IL-15 compared to untargeted therapeutics." (PMID 38338686, 2024).